YTHDC1 (YTH N6-methyladenosine RNA binding protein C1)
Description:
Regulator of alternative splicing that specifically recognizes and binds N6-methyladenosine (m6A)-containing RNAs. M6A is a modification present at internal sites of mRNAs and some non-coding RNAs and plays a role in the efficiency of mRNA splicing, processing and stability. Acts as a key regulator of exon-inclusion or exon-skipping during alternative splicing via interaction with mRNA splicing factors SRSF3 and SRSF10. Specifically binds m6A-containing mRNAs and promotes recruitment of SRSF3 to its mRNA-binding elements adjacent to m6A sites, leading to exon-inclusion during alternative splicing. In contrast, interaction with SRSF3 prevents interaction with SRSF10, a splicing factor that promotes exon skipping: this prevents SRSF10 from binding to its mRNA-binding sites close to m6A-containing regions, leading to inhibit exon skipping during alternative splicing. May also regulate alternative splice site selection. Also involved in nuclear export of m6A-containing mRNAs via interaction with SRSF3: interaction with SRSF3 facilitates m6A-containing mRNA-binding to both SRSF3 and NXF1, promoting mRNA nuclear export. Involved in S-adenosyl-L-methionine homeostasis by regulating expression of MAT2A transcripts, probably by binding m6A-containing MAT2A mRNAs (By similarity). Also recognizes and binds m6A on other RNA molecules. Involved in random X inactivation mediated by Xist RNA: recognizes and binds m6A-containing Xist and promotes transcription repression activity of Xist. Also recognizes and binds m6A-containing single-stranded DNA. Involved in germline development: required for spermatogonial development in males and oocyte growth and maturation in females, probably via its role in alternative splicing (By similarity). Independently of its N6-methyladenosine-containing RNA reader activity, it regulates PPARG stability by preventing its interaction with the E3 ubiquitin ligase ARIH2, thereby protecting it from ubiquitin-mediated proteasomal degradation and contributing to brown adipose tissue (BAT) development and energy homeostasis (By similarity).
Synonyms: YT521-B; KIAA1966; YT521
Tractability: Small molecule: a structure with a bound ligand is known. Antibody: its Gene Ontology location is reachable by antibodies, with high confidence; the Human Protein Atlas places it where antibodies can reach. PROTAC: UniProt records ubiquitination sites on it; ubiquitination databases record sites on it; its protein half-life has been measured.
Gene: Protein-coding gene on chromosome 4 (68,310,387 to 68,350,098, reverse strand). Ensembl gene ENSG00000083896.
Subcellular location: Nucleus; Nucleus speckle
Subcellular location (Human Protein Atlas): Nucleoplasm; Plasma membrane
Pathways (Reactome):
Metabolism of RNA: Nuclear RNA decay
Gene Ontology:
Molecular function: N6-methyladenosine-containing RNA reader activity; protein binding; RNA binding; molecular sequestering activity
Biological process: dosage compensation by inactivation of X chromosome; mRNA export from nucleus; mRNA splice site recognition; regulation of mRNA splicing, via spliceosome; brown fat cell differentiation; mRNA splicing, via spliceosome; post-transcriptional regulation of gene expression; regulation of alternative mRNA splicing, via spliceosome; mRNA processing
Cellular component: nuclear speck; nucleus; nucleoplasm
Genetic constraint (gnomAD): Loss-of-function variants: 10 observed, 92.37 expected, observed/expected ratio (o/e) 0.11, 90% interval 0.066 to 0.18. The upper end of that interval is the gene's LOEUF score, 0.18, which puts it in group 1 of 6, group 1 being the genes least tolerant of losing a copy. Missense variants: 587 observed, 864.16 expected, observed/expected ratio (o/e) 0.68, 90% interval 0.63 to 0.73. Synonymous variants: 252 observed, 277.75 expected, observed/expected ratio (o/e) 0.91, 90% interval 0.82 to 1.01.
Homologues: Orthologues: chimpanzee YTHDC1 (99% identical), dog YTHDC1 (98% identical), pig YTHDC1 (98% identical), macaque YTHDC1 (97% identical), mouse Ythdc1 (97% identical), rat Ythdc1 (97% identical), guinea pig YTHDC1 (91% identical), rabbit YTHDC1 (85% identical), tropical clawed frog ythdc1 (78% identical), zebrafish ythdc1 (67% identical), Drosophila melanogaster Ythdc1 (26% identical). Paralogues in human: YTHDF2 (14% identical), YTHDF3 (13% identical), YTHDF1 (13% identical).
Diseases named in the same sentence as YTHDC1 in open-access papers:
YTHDC1 is named in the same sentence as 125 diseases in open-access papers, as found by Europe PMC text mining. Sharing a sentence is not in itself a finding about the gene and the disease. The quoted sentences say what the papers report.
bladder cancer (21 papers, 2020 to 2025). "In our study, we found that YTHDC1 is not only regulated by high-glucose conditions but also downregulated in bladder cancer tissue and associated with the prognosis of cancer." (PMID 37258572, 2023). "Together, these data indicate that YTHDC1 is associated with the prognosis of patients with bladder cancer." (PMID 37258572, 2023). "In our study, we revealed that YTHDC1 is not only regulated by high-glucose conditions but is also downregulated in bladder cancer tissue and associated with the prognosis of cancer." (PMID 37258572, 2023). "Next, we explored the underlying mechanism by which YTHDC1 inhibits the malignant progression of bladder cancer cells." (PMID 37258572, 2023). "Then an RNA binding protein-related bladder cancer prognostic model was constructed in which YTHDC1 acted as an independent prognosis-associated RNA-binding protein." (PMID 35501308, 2022). "Moreover, the low expression of YTHDC1 suggested poor sensitivity to cisplatin and was associated with worse overall survival in patients with bladder cancer." (PMID 37915034, 2023). "Our observations in multiple cell lines and human tissue samples support a tumor-suppressing role for YTHDC1 in bladder cancer, which is consistent with previous findings demonstrating enhanced tumor growth and chemoresistance in YTHDC1-depleted xenografts." (PMID 39741187, 2025). "Our findings establish YTHDC1-dependent m6A reading as a critical epitranscriptomic mechanism regulating bladder cancer invasiveness and provide a paradigm for the epitranscriptomic deregulation of cancer-associated networks." (PMID 39741187, 2025). "Here, we show that the m6A reader YTHDC1 is downregulated in muscle-invasive bladder cancer and is negatively correlated with the expression of epithelial‒mesenchymal transition genes." (PMID 39741187, 2025). "The YTHDC1/GLUT3/RNF183 axis establishes a positive feedback loop that regulates bladder cancer progression and glucose metabolism." (PMID 40271153, 2025). "YTHDF2 promotes progression of bladder cancer, whereas YTHDC1 can increase drug sensitivity and inhibit progression of malignancy." (PMID 40133252, 2025). "Our findings indicate that the ubiquitin E3 ligase XIAP promotes metastasis of bladder cancer cells by degrading YTHDC1." (PMID 40133252, 2025). "Our functional studies have shown that XIAP upregulated expression of MMP-2 by downregulating YTHDC1 and promoting metastasis of bladder cancer cells." (PMID 40133252, 2025). "YTHDC1 abnormalities have recently been noted in not only germline development but also human malignancies, including bladder cancer, lung cancer, and breast cancer." (PMID 40133252, 2025). "Immunohistochemical analysis of specimens from the 17 pairs of patients with bladder cancer showed that YTHDC1 expression was markedly lower in bladder cancer tissue than in adjacent normal tissue." (PMID 40133252, 2025). "Reportedly, YTHDC1 and glucose transporter 3/ring finger protein 183 form a feedback loop to regulate bladder cancer development and glucose metabolism." (PMID 39827178, 2025). "In this study, we demonstrated that XIAP is also a ubiquitin E3 ligase of YTHDC1, accelerating the degradation of YTHDC1 and promoting metastasis of bladder cancer." (PMID 40133252, 2025). "The research involved analyzing bladder cancer samples and conducting experiments on cell models, using RNA sequencing (a method to study the sequence of RNA) and other techniques to understand YTHDC1’s role in cancer progression." (PMID 39741187, 2025). "Researchers have identified a protein called YTHDC1, which reads specific RNA modifications (chemical changes to RNA that affect its function), as being less present in more aggressive cases of bladder cancer." (PMID 39741187, 2025). "We also examined the expression of YTHDC1 in bladder cancer cells with knockout, knockdown, and overexpression of XIAP by western blotting." (PMID 40133252, 2025).
bladder cancer (continued). "Silencing YTHDC1 in bladder cancer cells reduced PTEN expression and activated PI3K/AKT signalling by destabilizing PTEN mRNA in an m6A‐dependent manner." (PMID 37070134, 2023). "To further verify the correlation between YTHDC1 expression and cisplatin‐induced DNA damage, we treated shNC and shYTHDC1 bladder cancer cells with cisplatin." (PMID 37070134, 2023). "As illustrated, lower YTHDC1 expressed cancer cells indicate poor cisplatin outcome in bladder cancer patients; lower YTHDC1 destabilizes PTEN mRNA, thus activates AKT‐associated DNA damage response and attenuates cisplatin‐induced DNA damage." (PMID 37070134, 2023). "We showed that MG132 treatment diminished the effect of GLUT3 on modulating the protein level of YTHDC1 in bladder cancer cells." (PMID 37258572, 2023). "Oppositely, cell viability was reduced in YTHDC1 over‐expressing bladder cancer cells, demonstrated with IC50 for cisplatin reduced from 38.31 ± 7.63 μM in Vector cells to 6.38 ± 5.49 μM in YTHDC1 over‐expressing T24 cells." (PMID 37070134, 2023). "We also showed that YTHDC1 suppresses the malignant progression of and the glycolytic process in bladder cancer cells in an m6A-dependent manner and determined that this effect is partially mediated by GLUT3." (PMID 37258572, 2023). "Among the different pathology of bladder cancer in TCGA datasets and 77 bladder cancer samples we collected, YTHDC1 strictly expressed in the T1 stage, whereas its level reduced when the disease progressed to or beyond the T2 stage." (PMID 37070134, 2023). "Above all, the results indicate that lower expression of YTHDC1 reduces the degree of cellular DNA damage in bladder cancer." (PMID 37070134, 2023). "Although the molecular mechanism by which GLUT3 upregulates RNF183 is not clear, we demonstrated that RNF183 is the key mediator through which GLUT3 destabilizes YTHDC1 in bladder cancer cells." (PMID 37258572, 2023). "Taken together, these data suggest that the GLUT3/RNF183 axis promotes YTHDC1 degradation in bladder cancer cells." (PMID 37258572, 2023). "Here, we identified a positive feedback loop, namely, YTHDC1/GLUT3/RNF183, to clarify the relationship between YTHDC1 and glucose metabolism in bladder cancer cells." (PMID 37258572, 2023). "We evaluated the expression of PTEN and YTHDC1 in a cohort of bladder cancer patient tissues we collected." (PMID 37070134, 2023). "Taken together, these data suggest that YTHDC1 inhibits the malignant progression of bladder cancer cells via GLUT3." (PMID 37258572, 2023). "Taken together, these results indicate that YTHDC1 plays a critical role in cisplatin resistance in bladder cancer." (PMID 37070134, 2023). "This study demonstrates that YTHDC1 in bladder cancer is a critical factor for cisplatin resistance." (PMID 37070134, 2023). "In a panel of 36 sections with bladder cancer, we found a significant positive correlation between levels of YTHDC1 and γ‐H2AX, as illustrated by higher YTHDC1 expressing tumours displayed with higher γ‐H2AX expression." (PMID 37070134, 2023). "The results of CCK-8 and colony formation assays indicated that knockdown of YTHDC1 increased the proliferation of bladder cancer cells." (PMID 37258572, 2023). "Next, we constructed T24 and U3 bladder cancer cells with stably YTHDC1 silencing lenti‐virus, and constructed T24 bladder cancer cells with stably YTHDC1 over‐expressing lenti‐virus to evaluate the effect of YTHDC1 on cisplatin resistance." (PMID 37070134, 2023). "The expression of YTHDC1 was reduced in patients with bladder cancer who had undergone chemotherapy." (PMID 37915034, 2023). "We also demonstrated for the first time that YTHDC1 is a critical factor in cisplatin resistance in bladder cancer." (PMID 37070134, 2023). "The discrepancy in YTHDC1 expression was also observed in different molecular subtypes of bladder cancer and higher YTHDC1 level was identified in the neuronal subtype." (PMID 37070134, 2023).
bladder cancer (continued). "In summary, we showed that the protein stability of YTHDC1 is regulated by GLUT3 in bladder cancer cells." (PMID 37258572, 2023). "By analysing TCGA bladder cancer dataset, it was found that YTHDC1 expresses at low level in tumour cells, especially in advanced tumour types." (PMID 37070134, 2023). "Based on the in vitro results demonstrated above, we next examined the effect of YTHDC1 on cisplatin resistance in bladder carcinoma xenograft." (PMID 37070134, 2023). "More investigation is expected to unveil the potential mechanism behind the biological functions of YTHDC1 in bladder cancer." (PMID 35501308, 2022). "We found that three genes were correlated with the prognosis of bladder cancer, namely YTHDC1, FTO, WTAP." (PMID 34521394, 2021). "P < 0.1 as the reference standard, we found that three genes were correlated with the prognosis of bladder cancer, namely YTHDC1, FTO, WTAP." (PMID 34521394, 2021). "Overall, these findings demonstrated that YTHDC1 acts as tumor suppressor in bladder cancer." (PMID 40133252, 2025). "We identified an XIAP/YTHDC1/MMP-2 pathway that promotes metastasis of bladder cancer." (PMID 40133252, 2025). "We are planning further investigation of the XIAP domain and its interactions with YTHDC1, which may be key in the treatment of bladder cancer." (PMID 40133252, 2025). "We then hypothesized that YTHDC1 may have an important role in regulation of XIAP during metastasis of bladder cancer." (PMID 40133252, 2025). "YTHDC1 inhibits progression of bladder cancer by reducing glycolysis." (PMID 40133252, 2025). "Moreover, overall survival in patients with bladder cancer was significantly longer in those with higher YTHDC1 expression than in those with low YTHDC1 expression." (PMID 40133252, 2025). "We hypothesize that YTHDC1 may be regulated by other ubiquitin E3 ligases, identification of which may provide another novel strategy for the treatment of bladder cancer." (PMID 40133252, 2025). "We have demonstrated that YTHDC1 is a critical factor in cisplatin resistance in bladder cancer." (PMID 37070134, 2023). "Furthermore, we also found a reduced YTHDC1 expression in bladder cancer patients who have received chemotherapy, as well as in bladder cancer cells." (PMID 37070134, 2023). "Low expression of YTHDC1 indicates cisplatin resistance in bladder cancer patients and cells." (PMID 37070134, 2023). "Thus, our results suggest that the downregulation of YTHDC1 contributes to the aggressive behaviors of bladder cancer cells." (PMID 37258572, 2023). "In addition, the results of the colony formation assay and nude mouse xenograft assay showed that YTHDC1 depletion enhanced bladder cancer cell growth in vitro and bladder tumor growth in vivo." (PMID 37258572, 2023). "Hence, we analysed IHC scores with YTHDC1 staining among 20 bladder cancer patients that have received cisplatin‐containing chemotherapy." (PMID 37070134, 2023). "Moreover, in a cohort of bladder cancer patients, the expression of YTHDC1 was positively correlated with PTEN and γ‐H2AX levels, and lower YTHDC1 levels were specifically found in chemo‐resistant patients." (PMID 37070134, 2023). "Besides, in 33 bladder cancer samples we collected, similar result that lower YTHDC1 indicated worse overall survival was identified." (PMID 37070134, 2023). "Finally, we showed that low expression of YTHDC1 was significantly correlated with an unfavorable prognosis in patients with bladder cancer." (PMID 37258572, 2023). "Collectively, our results demonstrate that YTHDC1 is expressed at low levels in bladder cancer." (PMID 37258572, 2023). "Notably, knockdown of YTHDC1 also activated some glucose metabolism-regulated pathways in bladder cancer cells." (PMID 37258572, 2023). "Given that GLUT3 is not an E3 ligase, GLUT3 might indirectly promote the degradation of YTHDC1 in bladder cancer cells." (PMID 37258572, 2023).